SCN8A (sodium voltage-gated channel alpha subunit 8)
Diseases named in the same sentence as SCN8A in open-access papers (continued):
Sharing a sentence is not in itself a finding about the gene and the disease.
Dravet syndrome (25 papers, 2015 to 2026). "Scn8a reduction of 25% to 50% resulted in delayed seizure onset and prolonged survival not only in a mouse model of SCN8A encephalopathy but also in Dravet Syndrome." (PMID 32880951, 2021). "Moreover, a 25–50% reduction in the Scn8a transcript can delay seizure onset and lethality not only in mouse models of Scn8a encephalopathy but also in the mouse model of Dravet syndrome." (PMID 39513870, 2024). "In a similar manner to Dravet syndrome, specific targeting of inhibitory interneurons in SCN8A DEE may be a novel therapeutic strategy." (PMID 39435659, 2024). "Moreover, administering GS967 -a selective blocker of Nav1.6- reduces spontaneous seizures and prolongs the survival of heterozygous mice of N1768D Scn8a and Scn1a+/− Dravet syndrome." (PMID 39513870, 2024). "However, impairment of PV interneuron excitability in Dravet syndrome is specific to the P18–P21 developmental time window, whereas in SCN8A DEE, PV interneuron activity is more markedly impaired in adulthood." (PMID 39435659, 2024). "While Sudden Unexpected Death in Epilepsy (SUDEP) is reported to occur in individuals with CDD, data from large cohort studies suggests the frequency of SUDEP within the CDD population is lower than for Dravet syndrome or SCN8A-DEE, given the frequencies of these disorders." (PMID 35795799, 2022). "This could reflect different mechanisms of apnea in different models, or that seizures were invoked in different ways: heat-induced in Dravet Syndrome mice vs. hippocampal-stimulated in Scn8a mutant mice." (PMID 35126041, 2021). "Furthermore, it was recently shown that antisense oligonucleotide treatment to decrease Scn8a (Nav1.6) expression was sufficient to rescue disease phenotypes in a Dravet Syndrome model of Scn1a haploinsufficiency." (PMID 34235638, 2021). "For example, although seizures may be worsened by carbamazepine in Dravet syndrome, this anticonvulsant may be helpful in some patients with SCN8A." (PMID 26933559, 2015). "Epileptic spasms are seen with SCN8A mutations, but this is not a seizure-type associated with Dravet syndrome." (PMID 26933559, 2015). "Our previous studies have shown that ASO-mediated rescue of PV interneuron firing reduces seizures and prevents SUDEP in a model of Dravet syndrome; a similar phenotype may be observed in SCN8A DEE, where rescue of depolarization block prevents seizures and SUDEP." (PMID 39435659, 2024). "The mortality rate was 3.2%, similar to that observed in other DEEs, such as SCN8A-DEE (5%), and other genetic DEEs (6%) and lower than Dravet syndrome (8.6%)." (PMID 39392525, 2025). "Gene therapies are in development for both SCN8A DEE and Dravet syndrome, and downregulation of Scn8a has been shown to reduce seizures in both disorders." (PMID 39435659, 2024). "For example, the mean seizure onset of 5 months old is similar for both Dravet syndrome and SCN8A-related encephalopathy, however, unlike Dravet syndrome the upper age limits in cases due SCN8A can be after one year." (PMID 26933559, 2015). "Similarly, synaptic transmission between PV interneurons and PCs is also impaired in Dravet syndrome, though unlike our findings in SCN8A DEE, intrinsic excitability deficits are restored in adult PV interneurons." (PMID 39435659, 2024).
Cognitive impairment (24 papers, 2013 to 2025). Abnormal cognition is characterized by deficits in thinking, reasoning, or remembering. "Mutations of the SCN8A gene encoding the NaV1.6 channel are associated with cognitive deficits and susceptibility to bipolar disorder." (PMID 41465576, 2025). "It seems that sodium channel blockers, including phenytoin, can be effective in patients with GoF SCN8A mutations; however, due to potential cognitive impairment that is undesirable in patients with encephalopathy, phenytoin should be considered as a last-resort drug." (PMID 38003469, 2023). "Studies in human genome selected one mutation in the SCN8A gene expressed NaV1.6 channels which may be responsible for motor and cognitive deficits of variable expressivity." (PMID 23409712, 2013). "Altered expression of Scn8a has been observed in humans with absence seizures and cognitive impairments." (PMID 37014118, 2023). "Mutations in SCN8A are associated with cognitive impairment with or without cerebellar ataxia (OMIM#613406) and with early infantile epileptic encephalopathy-13 (EIEE13, OMIM#614558)." (PMID 27900360, 2016). "Given that AEDs can yield improvement across some symptom domains (seizures and affective symptoms), this points toward a likely distinct mechanism of attention and cognitive impairments, as they remained resistant to VPA treatment in Scn8a+/-mice." (PMID 37014118, 2023). "This is consistent with observations in a number of genetic epilepsies, including SCN8A, that cognitive deficits precede seizure onset or occur in the absence of significant seizure burden." (PMID 40925365, 2025).
developmental and epileptic encephalopathy (24 papers, 2020 to 2026). An epilepsy associated with developmental impairment that may be due to either the underlying etiology or the superimposed epileptic activity, or both. "Pathogenic variants in SCN8A, which encodes the voltage-gated sodium (NaV) channel NaV1.6, associate with neurodevelopmental disorders, including developmental and epileptic encephalopathy." (PMID 38771640, 2024). "The phenotypes associated with SCN8A pathogenic variants range in severity—from benign to severe developmental and epileptic encephalopathies (DEEs) with seizures of multiple types." (PMID 35802036, 2022). "SCN8A missense variants with gain-of-function channel properties are associated with developmental epileptic encephalopathy with early onset of severe seizures, hypotonia, and paroxysmal dyskinesia." (PMID 35557557, 2022). "Variants in the voltage-gated sodium channel gene SCN8A cause a severe developmental and epileptic encephalopathy (DEE) characterized by treatment-resistant seizures, developmental delay, long-term cognitive and motor impairment, and elevated risk of premature death." (PMID 41679675, 2026). "ASOs can downregulate the expression of the encoded sodium channel subunit NaV1.6 and have been shown to decrease seizures and mortality in genetic mouse models of SCN8A developmental and epileptic encephalopathy." (PMID 39917784, 2025). "The most severe of these epilepsy syndromes is SCN8A developmental and epileptic encephalopathy (SCN8A-DEE)." (PMID 35234610, 2022). "NBI-921352 is entering phase II proof-of-concept trials for the treatment of SCN8A-developmental epileptic encephalopathy (SCN8A-DEE) and adult focal-onset seizures." (PMID 35234610, 2022). "PCDH19, PLCB1, SCN8A, and HCN1 variations were found in Late Infantile Developmental and Epileptic Encephalopathy (LIDEE) patients." (PMID 41153369, 2025). "SCN8A GOF variants are associated with a wide spectrum of pediatric disorders ranging from benign familial seizures to severe developmental and epileptic encephalopathy (DEE)." (PMID 38348743, 2024). "Our survival analysis indicated SUDEP first occurred after two months of age in both male and female mutants, which is four to six weeks later than common monogenic developmental epileptic encephalopathy SUDEP models, such as Scn1a, Scn8a and Kcna1 mutants." (PMID 34396109, 2021). "Pathogenic variants in the voltage-gated sodium channel gene, SCN8A (encoding NaV1.6), underlie a wide spectrum of clinical phenotypes ranging from neurodevelopmental delays (NDD) with or without seizures—to severe developmental and epileptic encephalopathy (DEE)." (PMID 40830973, 2025).
Encephalopathy (23 papers, 2015 to 2025). Encephalopathy is a term that means brain disease, damage, or malfunction. "In SCN8A encephalopathy, pathogenic variants lead to gain-of-function mutations in the SCN8A gene, and this results in persistent sodium currents through the NaV1.6 channel and increased neuronal excitability." (PMID 40290041, 2025). "Failures of precision therapies should be not underestimated, e.g., quinidine (and its derivatives) in KCNT1-activating mutations or phenytoin in patients with GoF SCN8A mutations and encephalopathy." (PMID 38003469, 2023). "In another case of a 5-year-old patient with a GoF SCN8A mutation and encephalopathy, phenytoin maintenance therapy led to rapid deterioration, with encephalopathy, ataxia, and somnolence." (PMID 38003469, 2023). "In general, GoF mutations seem to be responsible for SCN8A-related encephalopathy, with seizures beginning within the first 18 years of life." (PMID 38003469, 2023). "SCN8A encephalopathy is caused primarily by gain-of-function mutations in the neuronal sodium channel (Nav1.6) and causes severe, early-onset seizures." (PMID 37583518, 2023). "Missense mutations of SCN8A, which encodes Nav1.6, one of the main voltage-gated sodium channel subunits in neurons and muscles, have been linked to early infantile SCN8A encephalopathy." (PMID 33915942, 2021). "Herein, we report the case of a 5-month-old girl with SCN8A encephalopathy with a novel missense mutation." (PMID 33915942, 2021). "Similar results were observed in a mouse with conditional Cre-dependent expression of a pathogenic mutation Scn8a-R1872W/+, a model of SCN8A encephalopathy." (PMID 33996898, 2021). "Seizures were induced by electrical stimulation of the hippocampus of a mouse carrying the human SCN8A encephalopathy mutation p.Asn1768Asp (N1768D; “D/+ mice”)." (PMID 35126041, 2021). "SCN8A encephalopathy caused by de novo GoF mutations in Nav1.6 results in neuronal hyperactivity." (PMID 32880951, 2021). "Astrocyte reactivity was observed after the onset of spontaneous seizures in a mouse model of SCN8A encephalopathy." (PMID 37583518, 2023). "Reduction of the levels of Scn8a transcript to 25–50% of typical expression levels using an ASO resulted in delayed seizure onset and increased survival in mouse models of both SCN8A encephalopathy and DS." (PMID 35250833, 2022). "Although phenytoin is recommended as a last-resort treatment for SCN8A encephalopathy, the administration of the oxcarbazepine, instead of phenytoin, mitigated this patient's intractable seizures." (PMID 33915942, 2021). "SCN8A encephalopathy is a severe genetic epilepsy syndrome and neurodevelopmental disorder characterized by refractory seizures, cognitive and motor dysfunction, and a substantial risk for SUDEP." (PMID 33762902, 2021). "Two knock‐in mouse models of SCN8A encephalopathy have been generated by inserting the less severe Scn8a N1768D and more severe R1872W GoF mutations that are observed in patients." (PMID 32880951, 2021). "Our results encourage future examination of various additional brain regions in models of SCN8A encephalopathy to more precisely identify the neuronal mechanisms responsible for the audiogenic seizures and sudden death." (PMID 33762902, 2021). "The D/+ mice recapitulate the key hallmarks of SCN8A encephalopathy and SUDEP: chronic spontaneous tonic-clonic seizures and seizure-induced deaths." (PMID 33762902, 2021). "Taken together, our results highlight the D/+ mouse model of SCN8A encephalopathy as a new useful model for mechanistic investigation of SUDEP." (PMID 33762902, 2021). "< e phenotypic spectrum of SCN8A encephalopathy Schefier IE, Mefiord HC, Møller RS; EuroEPINOMICS RES Consortium CRP." (PMID 29291359, 2017). "Our findings also suggest that SCN8A-related encephalopathies may be underrecognized as progressive imaging disorders, particularly when early scans appear normal." (PMID 41573391, 2025).
Encephalopathy (continued). "The clinical manifestations of SCN8A encephalopathy are likely reliant on the degree of GoF or LoF." (PMID 38233770, 2024). "Many studies show that sodium channel inhibitors might be the most effective treatment approach for individuals with SCN8A encephalopathy." (PMID 40217485, 2023). "Although the treatment options with proven efficacy do exist for individuals with SCN8A encephalopathy, reports from several patients suggest that levetiracetam is ineffective at controlling seizures and may even worsen the symptoms." (PMID 40217485, 2023). "In addition, developmental disabilities were expressed in the mice, characterized by skewed postures, impeded movements, and tremors, which are typical of SCN8A encephalopathies." (PMID 33841294, 2021). "While transgenic mouse models have provided insight into the molecular mechanisms of SCN8A encephalopathy etiology, our understanding of seizure-induced death has been hampered by the inability to reliably trigger both seizures and seizure-induced death in these mice." (PMID 33762902, 2021). "To date, there have been no reports of SCN8A encephalopathy patients that exhibit hearing abnormalities or audiogenic seizures." (PMID 33762902, 2021).
developmental delay (17 papers, 2016 to 2026). "Deficiencies in Scn8a expression are related to infantile epilepsy and developmental delays in humans." (PMID 39998310, 2025). "In conclusion, the identification of a heterozygous mutation in the SCN8A gene, specifically the p.Phe210Ser variant, in our patient provides valuable insights into the underlying etiology of their refractory epilepsy and developmental delays." (PMID 38846250, 2024). "Additionally, the majority of individuals with SCN8A mutations experience varying degrees of global developmental delay, ranging from mild to severe." (PMID 38846250, 2024). "Finally, a male patient with a SCN8A missense variant (c.5246A>G, p.Y1749C) exhibited psychomotor delay and ischemic changes on MRI, highlighting the contribution of SCN8A variants to LIDEE phenotypes characterized by developmental delay and multifocal epileptiform activity." (PMID 41153369, 2025). "Early seizure onset and developmental delays are hallmarks of SCN8A-related DEE." (PMID 38846250, 2024).
cervical cancer (14 papers, 2014 to 2025). A primary or metastatic malignant neoplasm involving the cervix. "In order to test the potential use of the abnormal expression of SCN8A gene as a molecular marker for invasive cervical cancer we performed a Receiver Operating Characteristic (ROC) curve analysis using the qPCR data from non-cancerous and CeCa samples." (PMID 30158710, 2018). "In summary, the results from this section show for the first time the expression of SCN8A splice forms during progression of human cervical cancer." (PMID 30158710, 2018). "Previous studies have already found that high expression of SCN8A could enhance the invasion of cervical cancer cells and that SCN9A could promote gastric cancer progression." (PMID 35126466, 2021). "However, further studies are needed to determine the potential use of the expression levels of SCN8A as a predictive or prognostic molecular marker for human cervical cancer." (PMID 30158710, 2018). "The results show that both 18N and Δ18 splice products of SCN8A were consistently amplified from all groups of samples studied here, although these products were clearly more abundant in samples of cervical cancer regardless of the oncogenic HPV type." (PMID 30158710, 2018). "Additionally, these deregulated SCN8A levels allowed to discriminate with high sensitivity and specificity cases of non-cancerous cervix from invasive cervical cancer." (PMID 30158710, 2018). "Thus, SCN8A gene is upregulated in most of human cervical cancer cases (around 90% of all) compared with both non-cancerous cervix and cervical intraepithelial neoplasia samples." (PMID 30158710, 2018).
channelopathies (14 papers, 2019 to 2025). "Several genes, especially channelopathies, have been identified in patients who died of SUDEP including gene variants associated with seizures (e.g., SCN1A, SCN8A, SCN2A) or long QT-Syndrome (SCN5A, KCNH2, KCNQ1)." (PMID 40703772, 2025). "In the case of six patients with variants in other channelopathy-related genes (SCN1A, SCN2A, SCN8A, and KCNQ2), the previous literature guided the choice of anti-seizure medication." (PMID 37645600, 2023). "Genetic mutations in KCNA1, CACNA1A, CACNB4, SLC1A3, SCN8A, KCNMA1, and ATP1A3 genes that encode ion channels lend support to the channelopathy theory." (PMID 37008993, 2023). "Given its pivotal role in neuronal signaling, it is not surprising that mutations in Nav1.6 associated with gain-of-function phenotypes promote hyperexcitability in SCN8A channelopathies." (PMID 35805192, 2022). "Among molecularly diagnosed cases SCN1A, SCN2A, KCNQ2, SCN8A, and ATP1A2 were identified as channelopathy-related genes, representing 7 patients." (PMID 40083435, 2025).
Dystonia (12 papers, 2013 to 2025). An abnormally increased muscular tone that causes fixed abnormal postures. "Importantly, the phenotypes associated with mutations in the DYT genes enriched in the putamen ‘cyan’ module belonged to different clinical subtypes of dystonia, namely isolated dystonia (ANO3 and HPCA), combined dystonia (KCTD17 and ADCY5), and paroxysmal dystonia (KCNA1, CACNA1A, PRRT2 and SCN8A)." (PMID 32889528, 2020).
neuroblastoma (9 papers, 2016 to 2024). Neuroblastoma (NB) is the most common solid, extracranial childhood tumor. "In contrast, RING1B depletion in 293T did not affect NaV1.6 levels while in neuroblastoma SK-N-SH cells caused subtle increases in SCN8A mRNA levels, suggesting that RING1B regulation of the NaV1.6 channel is specific of ES cells." (PMID 27317769, 2016).
Alzheimer disease (8 papers, 2016 to 2025). A progressive, neurodegenerative disease characterized by loss of function and death of nerve cells in several areas of the brain leading to loss of cognitive function such as memory and language. "The 17th SNP resides in the gene SCN8A, which is one of the few genes that have been reported to be associated with Alzheimer’s disease through pathway analysis in mouse model." (PMID 31881907, 2019).
autism (8 papers, 2014 to 2024). Persistent deficits in social interaction and communication and interaction as well as a markedly restricted repertoire of activity and interest as well as repetitive patterns of behavior. "In this regard, preclinical studies have suggested that patients with mutations in SCN8A, the gene encoding for voltage-gated sodium channel subunit 8 and that is associated with seizures, movement disorders, and autism, could result in a reduction in seizures with CBD treatment." (PMID 35629320, 2022). "The SCN8A R1620L mutation was previously identified in a patient that presented with a wide range of behavioral abnormalities, including social behavior deficits, autism, attention deficit hyperactivity disorder, and behavioral seizures without accompanying electrographic activity." (PMID 35153788, 2022). "PC Scn8a mutant mice were previously shown to be impaired in delay eyeblink conditioning, an additional connection to cerebellar dysfunction and autism." (PMID 35557557, 2022). "Given the similarity of the PC Scn8a mutant mice to other autism models with regards to motor deficit, delay eye-blink conditioning impairment and electrophysiological changes in Purkinje cells, it is not surprising that PC Scn8a mutant mice also exhibit ASD-relevant social deficits." (PMID 35557557, 2022).